SIRT1 (sirtuin 1)
Diseases named in the same sentence as SIRT1 in open-access papers (continued):
Sharing a sentence is not in itself a finding about the gene and the disease.
steatosis (continued). "Therefore, inhibition of SIRT1 activity by ethanol feeding was related to an increase in the acetylated form of SREBP-1c, and consequently leading to the development of steatosis." (PMID 33162823, 2020). "Based on steatosis results, we aimed to verify the hypothesis that silibinin may influence NAD+ levels and the SIRT1/AMPK pathway." (PMID 28973994, 2017). "Whether miR-34a/SIRT1 involved in the induction of steatosis mediated by HCD, in particular, if there is difference in miR-34a expression and SIRT1 protein level between isocaloric pair-fed HCD vs. HFD in mice is unknown." (PMID 26608583, 2015). "Indeed, the decreased mRNA expressions of fatty acid oxidation related genes Cpt1, Ppara and Pgc1a also supported the involvement of SIRT1/AMPK in the decreased fatty acid oxidation, and subsequently promoted the steatosis mediated by HCLD feeding." (PMID 26608583, 2015). "Another key finding in this study was that Sirt1 and Sir6 were not synergistic but compensatory factors that prevented hepatocyte steatosis based on the results of the Sirt1/6 single and double knockdown experiment." (PMID 25133775, 2014). "Our results demonstrate that Sirt1/6 are involved in the RGZ-mediated effects on hepatocyte steatosis, and the regulatory effects of Sirt1 and Sirt6 are not synergistic but compensatory for improving hepatocyte steatosis." (PMID 25133775, 2014). "On the other hand, RGZ’s effects on Sirt6 were not altered by Sirt1 knockdown in a hepatocyte steatosis model." (PMID 25133775, 2014). "The aim of this study was to address whether rosiglitazone (RGZ) alters hepatic Sirt1 and whether Sirt1 and/or Sirt6 have a regulatory role in the protective effects of RGZ on hepatocyte steatosis." (PMID 25133775, 2014). "The present study was designed to test whether RGZ alters hepatic Sirt1 and whether Sirt1 and/or Sirt6 have a regulatory role in the protective effects of rosiglitazone (RGZ) on hepatocyte steatosis." (PMID 25133775, 2014). "Additionally, the results of AH patients, NIAAA, and ALD mouse models have indicated that excessive alcohol consumption inhibits the ADRB2/SIRT1/PGC-1α/PPARα pathway, leading to elevated levels of oxidative stress and cytokines such as CCL2, CXCL8, and CXCL10, accompanied by hepatic steatosis." (PMID 39640486, 2024).
Parkinson disease (96 papers, 2012 to 2026). A progressive degenerative disorder of the central nervous system characterized by loss of dopamine producing neurons in the substantia nigra and the presence of Lewy bodies in the substantia nigra and locus coeruleus. "In a rodent model of Parkinson’s disease, overexpression of SIRT1 caused a reduction in alpha synuclein aggregates and increased longevity while knockout mice displayed opposite effects." (PMID 30504847, 2018). "SIRT1, the best studied mammalian SIRT is involved in many physiological and pathological processes and changes in SIRT1 have been implicated in neurodegenerative disorders, with SIRT1 having a suggested protective role in Parkinson’s disease." (PMID 28578695, 2017). "Interestingly, high serum levels of SIRT1 were associated with higher cognitive performance in Parkinson’s disease patients compared to individuals with lower SIRT1 levels; hence, it is likely that SIRT1 plays an important role in memory." (PMID 39683482, 2024). "In this study, serum SIRT1 levels were found to be significantly lower in patients with Parkinson’s disease (PD) than in healthy controls, reflecting a marked decline in this key neuroprotective and metabolic regulator." (PMID 41601525, 2026). "It engages AMPK and SIRT1, and helps reduce autophagy and inflammation in models of Parkinson’s disease and Alzheimer’s." (PMID 41516357, 2026). "Atractylenolide‐I attenuates oxidative stress and Parkinson's disease–related pathology by activating the SIRT1/PGC‐1α/Nrf2 signaling axis." (PMID 41502826, 2026). "Recent research has revealed two promising therapeutic strategies for Parkinson's disease targeting the AMPK/SIRT1/PGC‐1α pathway." (PMID 41268687, 2025). "EMPA has also been shown to contribute to mitochondrial protection and redox balance by activating the AMPK/SIRT-1/PGC-1α axis in rotenone-induced Parkinson’s disease model." (PMID 41011131, 2025). "For instance, SRT1720, a well‐characterized SIRT1 activator, has demonstrated efficacy in a paraquat (PQ)‐induced Parkinson's disease mouse model." (PMID 41208649, 2025). "Resveratrol inhibits ferroptosis via the SIRT1/NRF2 pathway in models of Parkinson's disease, including cells, mice, and nematodes." (PMID 41220093, 2025). "Huang, Duan reported the connection between amelioration of Parkinson’s disease and SIRT-1 activation." (PMID 41471276, 2025). "There is compelling evidence to support the fact that SIRT1 is shuttled between the nucleus and cytoplasm and perform context-dependent functions in neurodegenerative diseases including Alzheimer’s disease, Parkinson’s disease, and Huntington’s disease." (PMID 37718350, 2024). "CBD enhances autophagy and mitochondrial function in human neuroblastoma cells (Parkinsonism in vitro model) by activating the SirT1 pathway." (PMID 36839877, 2023). "SIRT1 and SIRT2 are the most abundant sirtuins in the brain, and both are highly associated with neurodegenerative diseases including AD, Parkinson's disease (PD), and Huntington's disease (HD)." (PMID 37602729, 2023). "SIRT1 activity has also demonstrated a neuroprotective role in slowing neurodegenerative disease progression in pathologies such as Parkinson’s disease (PD) and amyotrophic lateral sclerosis (ALS) by upregulating autophagy." (PMID 37456463, 2023). "Next, we examined the contribution of the proteasome pathway, as SIRT1 has been shown to be degraded by the proteasome in a Parkinson’s disease mouse model." (PMID 36230925, 2022). "A prospective therapy alternative for neurological diseases, such as Alzheimer’s, Parkinson’s, and Huntington’s disease as well as for the prevention and the advancement of neuroinflammaging, is now thought to include SIRT1 and the other sirtuins." (PMID 35893883, 2022). "Other substrate of SIRT1 such as NF-κB has been found changed and involved in microglial polarization in Parkinson’s disease models." (PMID 36111151, 2022).
Parkinson disease (continued). "More and more studies have confirmed that SIRT1 plays an important role in the development of neurodegenerative diseases, such as AD, Parkinson's disease (PD), or ischemic stroke." (PMID 34239694, 2021). "In neurons, miR-138-5p is involved in the progression of Parkinson’s disease by regulating the inflammatory response via the SIRT1 axis." (PMID 32678044, 2020). "In line with this concept, a previous study demonstrated the neuroprotective activity of cilostazol via SIRT1-autophagy activation in rat Parkinson’s disease model." (PMID 32820458, 2020). "The effect of resveratrol on SIRT1 signaling has also been tested in prolonged life span, Parkinson's disease, obesity, amyotrophic lateral sclerosis, diabetic milieu, and trauma-hemorrhage shock." (PMID 26301045, 2015). "Within the brain Sirt1 is indispensable for normal cognitive function and its activation protects against neurodegenerative diseases including Parkinson's, Alzheimer's and Huntington's disease in animal models." (PMID 24416337, 2014). "Lastly, the miR-34 family target SIRT1 to affect tau metabolism, are decreased in Parkinson's disease patients and show increased expression in the presence of mutant HTT." (PMID 24133413, 2013). "SIRT1 and caloric restriction show neuroprotective properties in mouse models for Alzheimer’s and Parkinson’s diseases." (PMID 23056585, 2012). "We hypothesize that patients with Parkinson’s disease exhibit decreased serum levels of SIRT1 and Nrf2 and increased NLRP3 inflammasome levels compared with healthy controls, reflecting impaired antioxidant defense and heightened inflammatory activation." (PMID 41601525, 2026). "In a Parkinson’s mouse model, SIRT1-mediated dehydrated to HSPA4 was shown to reduce neuritis." (PMID 40076916, 2025). "Also, EMPA enhanced the AMPK/SIRT-1/PGC-1α pathway in a rat model of Parkinsonism induced by rotenone." (PMID 40325262, 2025). "SIRT1 plays protective roles in several neurodegenerative diseases, including Alzheimer’s, Parkinson’s, and motor neuron diseases, which may relate to its functions in metabolism, stress resistance, and genomic stability." (PMID 38672209, 2024). "MiR-141-3p was also reported to target and inhibit the expression of SIRT1 in Parkinson’s disease." (PMID 38261732, 2024). "In Parkinson’s disease models, SIRT1 signaling pathway is involved in NLRP3 inflammasome activation in microglia, that has been proved again in an subarachnoid hemorrhage mice model in which SIRT1 not only involved in microglia activation, but also M2 microglial polarization." (PMID 36111151, 2022). "Sirt1 has been shown to play protective roles in several neurodegenerative diseases including Alzheimer’s, Parkinson’s, and motor neuron diseases, which may relate to its functions in metabolism, stress resistance, and genomic stability." (PMID 34530866, 2021). "Besides, the neurotoxic and proinflammatory roles of miR-9-5p have been highlighted in Parkinson’s disease by inhibiting SIRT1." (PMID 34743197, 2021). "Indeed, Sirt1 plays protective roles in some neurodegenerative diseases, including motor neuron diseases, and Parkinson’s disease." (PMID 33987177, 2021). "Additionally, SIRT1 activity has been demonstrated to confer neuroprotection in several age-related neurodegenerative disorders including Parkinson’s and Alzheimer’s diseases and metabolism related disorders." (PMID 31973227, 2020). "Indeed SIRT1 is highly protective in both in vitro and in vivo models of Alzheimer’s disease (AD), Huntington’s disease (HD), Parkinson’s disease (PD), amyotrophic lateral sclerosis (ALS), and the response to strokes." (PMID 30973934, 2019).
Parkinson disease (continued). "In addition to its important role of normal brain aging process, SIRT1 has also been shown to improve a series of neurodegenerative disorders in animal models including Alzheimer’s, Parkinson’s, and Huntington’s disease." (PMID 30426321, 2019). "To date, there is a limited number of studies linking Parkinson's disease (PD) and SIRT1." (PMID 23417962, 2013). "In addition, SIRT1 enhances synaptic formation and synaptic activity, therefore can reduce the progression of various degenerative brain diseases like Alzheimer’s disease (AD) and Parkinson’s disease (PD)." (PMID 36580159, 2023). "In conclusion, the gastrointestinal function of the MPTP + Cur mice could not be improved after sirtinol treatment, further confirming that curcumin could reduce intestinal inflammation and, thus, improve gastrointestinal dysfunction in Parkinson’s disease mice by activating the SIRT1/NRF2 pathway." (PMID 36678536, 2022). "Given the intertwined roles of SIRT1, Nrf2, and NLRP3 in regulating neuroprotection, oxidative stress responses, and inflammasome-mediated inflammation, evaluating these pathways together may provide deeper mechanistic insight into the redox–inflammatory imbalance underlying Parkinson’s disease." (PMID 41601525, 2026). "In human neuroblastoma cells (in vitro Parkinson model), CBD activated the SIRT1 pathway, increasing the autophagy and mitochondrial activity." (PMID 40426994, 2025). "In neurodegeneration models, AGK2, a sirtuin inhibitor with higher selectivity for SIRT2 (IC50 for SIRT1 >50 μM and SIRT2 23.5 μM, respectively) showed protection from alpha-synuclein toxicity in Parkinson’s disease model." (PMID 31973227, 2020). "Sirtuin 1 (SIRT1) plays protective roles against several neurodegenerative diseases including Alzheimer’s, Parkinson’s, and motor neuron diseases." (PMID 32372957, 2020). "As in Parkinson’s disease, in ALS, it was demonstrated that Sirt1 deacetylates the heat shock factor 1 (HSF1) upregulating hsp70 and hsp25 prolonging the lifespan of motor neurons." (PMID 30304806, 2018). "Resveratrol whose functions include activation of SIRT1 also offered protection in this model, as well as in MPTP-induced mouse Parkinsonism." (PMID 27882448, 2017). "SIRT1 regulates pathways responsible for NSC maintenance and differentiation including cell cycle progression, autophagy in neurons, and neurodegeneration as described for NSCs in Parkinson’s disease." (PMID 37728850, 2024). "As oxidative stress has a role in the pathophysiology of neurodegenerative diseases, such as Parkinson’s disease, Nrf2 thereby, for example, AMPK/SIRT1/Nrf2 pathway may be an important therapeutic target in the treatment of these diseases." (PMID 34206738, 2021). "To determine whether this reduction was specific to patients with dementia, we analyzed SIRT1 and SIRT2 expression in buffy coat samples from patients with parkinsonism." (PMID 35008438, 2021). "These have not been analysed previously in the context of Parkinson’s disease pathogenesis, in contrast to other sirtuin family members (Sirt1, Sirt2, and Sirt3)." (PMID 27763519, 2016). "Numerous studies have shown that curcumin may improve Parkinson’s disease, but the exact mechanism has not been fully clarified, while some studies suggest that curcumin improves intestinal inflammation, possibly by activating the SIRT1/NRF2 pathway." (PMID 36678536, 2022). "However, the combined evaluation of SIRT1, Nrf2, and NLRP3 in patients with Parkinson’s disease has not been thoroughly investigated, particularly in relation to clinical outcomes such as fatigue and quality of life." (PMID 41601525, 2026).
osteoarthritis (95 papers, 2011 to 2026). A noninflammatory degenerative joint disease occurring chiefly in older persons, characterized by degeneration of the articular cartilage, hypertrophy of bone at the margins and changes in the synovial membrane. "The senescence‐associated miRNA mir‐34a, which is known to target Wnt and Notch pathways as well as the cell survival factors Sirt1 and Bcl2, is detected in EVs from human and animal subjects with muscle atrophy, bone loss, and osteoarthritis." (PMID 36398109, 2022). "Pharmacological blockade of SIRT1 effectively reduced the severity of osteoarthritis caused by the DOT1L inhibitor, and reversed the hyper-activation of Wnt signalling." (PMID 28627522, 2017). "More recently, it has been shown that SIRT1 prevents human chondrocyte apoptosis, suppresses catabolic changes in gene expression, and accelerates osteoarthritis in conditional SIRT1-deficient mice." (PMID 26373839, 2015). "Indeed, SIRT1 is a key regulator of mitochondrial biogenesis, and its cytoplasmic depletion has been associated with the progression of osteoporosis and arthrosis in mouse models." (PMID 40956314, 2025). "Notably, SRT3025 treatment increases PGC-1α mRNA and protein levels through activating SIRT1 in femoral MSCs in female patients undergoing hip operations caused by fracture or osteoarthritis." (PMID 36632457, 2023). "However, the exact mechanism of SIRT1 activation in chondrocytes and its role in age-associated osteoarthritis are poorly understood." (PMID 37762053, 2023). "Osteoarthritis is linked to the changes in Sirt1 activity in the cartilage." (PMID 35874275, 2022). "Sirtuin-1 has been implicated in the senescence of chondrocytes and pathogenesis of osteoarthritis." (PMID 30186176, 2018). "Inhibition of SIRT1 protects against osteoarthritis triggered by loss of DOT1L activity." (PMID 28627522, 2017). "These two reports suggest that SIRT1 plays a positive role in the maintenance of chondrocyte homeostasis, the loss of which may lead to the development of osteoarthritis." (PMID 22152608, 2011). "As decreased SIRT1 signaling is associated with advanced age, these findings suggest that downregulated SIRT1 activity may be common to both age-related and injury-induced osteoarthritis." (PMID 37047494, 2023). "In searching for the potential molecular mechanism underlying FA‐mediated suppression of IL‐1β‐induced osteoarthritis chondrocyte degeneration, we identified the SIRT1/AMPK/PGC‐1α signaling pathway might be an important cascade mediating the protective effects of FA." (PMID 34078001, 2021). "In vivo, fisetin administration attenuated joint degeneration in mice with induced osteoarthritis, as well as reducing subchondral bone plaque thickness and alleviating synovitis, confirming its efficacy in modulating disease progression through SIRT1." (PMID 40806700, 2025). "In bone marrow mesenchymal stem cells, NRF2/GPX4 activation enhances osteogenic capacity under oxidative stress, while in chondrocytes, SIRT1/NRF2/HO-1 signaling mitigates osteoarthritis progression by suppressing ferroptosis." (PMID 41199365, 2025). "Metformin mitigates cholesterol accumulation via the AMPK/SIRT1 pathway to protect osteoarthritis chondrocytes and regulate plasma lipids." (PMID 40510834, 2025). "In osteoarthritis, by deacetylating key proteins, SIRT1 activates the antioxidant response element (ARE), thereby upregulating the expression of antioxidant genes such as Nrf2, HO-1, and GPX4." (PMID 40109363, 2025). "Taken together, our study demonstrated that metformin inhibited chondrocyte senescence and promoted chondrocyte proliferation through microRNA-34a/SIRT1 pathway in osteoarthritis." (PMID 36915137, 2023).